OR2T27 (olfactory receptor family 2 subfamily T member 27)
Description:
Odorant receptor.
Tractability: Antibody: UniProt places it where antibodies can reach, with medium confidence; UniProt predicts a signal peptide or a membrane-spanning region; its Gene Ontology location is reachable by antibodies, with medium confidence.
Gene: Protein-coding gene on chromosome 1 (248,649,838 to 248,655,528, reverse strand). Ensembl gene ENSG00000187701.
Subcellular location: Cell membrane
Pathways (Reactome):
Sensory Perception: Expression and translocation of olfactory receptors
Gene Ontology:
Molecular function: olfactory receptor activity; G protein-coupled receptor activity
Biological process: detection of chemical stimulus involved in sensory perception of smell; G protein-coupled receptor signaling pathway
Cellular component: plasma membrane; membrane
Genetic constraint (gnomAD): Loss-of-function variants: 0 observed, 0.46 expected, observed/expected ratio (o/e) 0, 90% interval 0 to 1.84. That is too few expected variants to judge how well the gene tolerates losing a copy. Missense variants: 128 observed, 153.52 expected, observed/expected ratio (o/e) 0.83, 90% interval 0.72 to 0.97. Synonymous variants: 45 observed, 55.89 expected, observed/expected ratio (o/e) 0.81, 90% interval 0.63 to 1.03.
Homologues: Orthologues: macaque OR2T27 (93% identical), dog OR2T27 (88% identical), pig OR2T27 (86% identical), guinea pig OR2T27 (81% identical). Paralogues in human: OR2T1 (70% identical), OR2T2 (68% identical), OR2T35 (67% identical), OR2T11 (64% identical), OR2T6 (63% identical), OR2T29 (61% identical), OR2T5 (61% identical), OR2T4 (60% identical), OR2T10 (56% identical), OR2T3 (56% identical), OR2T34 (55% identical), OR2AK2 (53% identical), and 80 more.